BRAF (B-Raf proto-oncogene, serine/threonine kinase)
Diseases named in the same sentence as BRAF in open-access papers (continued):
Sharing a sentence is not in itself a finding about the gene and the disease.
tumor (continued). "In total, tumor-informed mutational analyses of cfDNA were performed in 309 samples from patients with RAS/BRAF mutant tumors, while DELFI-TF analyses were performed in 689 samples from patients in both RAS/BRAF mutant and wild-type tumors." (PMID 39433569, 2024). "The organoids with clustered regularly interspaced short palindromic repeats-Cas9 (CRISPR-Cas9) which incorporate common genetic alterations [Kras or B-Raf proto-oncogene (BRAF)] revealed a specific tumor niche and prognostic gene markers representing human serrated CRC." (PMID 38745769, 2024). "Considering the tumor’s response to therapies, which varies based on its molecular environment, molecular profiling also plays a crucial role, and it is targeted mainly towards BRAF, NRAS, and c-KIT genes." (PMID 39519055, 2024). "This suggests that intra- and inter-patient tumour heterogeneity may be a critical feature in resistance to BRAF inhibition." (PMID 38177660, 2024). "By contrast, the number of SNPs with a high/moderate or only a moderate impact on a protein structure/function was significantly higher in the BOT without the BRAF V600E mutation compared to all the remaining tumor groups." (PMID 39456660, 2024). "Differences in outcomes with anti-EGFR treatment in mCRC may be attributed to tumor genomic and molecular profiles associated with primary resistance to EGFR inhibition, such as the BRAF V600E mutation and high microsatellite instability (MSI-H), among others." (PMID 38347302, 2024). "Therefore, the introduction of specific BRAF-inhibitors had represented a crucial point in the treatment of this neoplasia." (PMID 36831417, 2023). "The discrepant IHC and molecular results surrounding the BRAF V600E status of this tumor may have suggested a possible role for BRAF or MEK inhibition." (PMID 37192626, 2023). "Nivolumab plus ipilimumab may have a superior benefit in patients with asymptomatic brain metastases and patients with BRAF-mutant tumours." (PMID 37404764, 2023). "In addition, BRAF, K-RAS, and N-RAS mutations were detected in 8 (3.0%), 78 (29.7%), and 68 (25.9%) tumor tissues, respectively." (PMID 37289436, 2023). "However, our data provide evidence for a robust tumor cell-intrinsic mechanism and support that BRAF/MAPK pathway activation promotes immune suppressive signals within tumor cells that can be reversed with targeted pathway inhibition." (PMID 36702949, 2023). "Therefore, the combination of clinically in-use kinase inhibitors (e.g., against the EGFR, BRAF or MEK1/2) with NHR ligands is a promising avenue for dual targeting of oncogenic signaling in tumor cells and simultaneous empowerment of host immunity." (PMID 37686465, 2023). "Randomization was stratified by tumour PD-L1 status (positive vs. negative; using a 5% cut-off of tumour expression assessed utilizing the same method as previously explained), BRAF mutational status, and advanced metastasis stage (M0-1b vs. M1c)." (PMID 37404764, 2023). "In the present study, we put forward that SPRY4 could be a key mediator for the observed differences in the phenotypes of T235 (BRAF mutant) and C3948 (BRAF wild type) cell lines, under macrophage modulation in the tumor microenvironment." (PMID 37686663, 2023). "However, in patients with CRC, BRAF inhibitor monotherapy is inactive against the tumor; thus, some efficacy would be unexpected." (PMID 36831331, 2023). "In addition, a proper evaluation of the preventive activity of statins towards BRAF-mutant CRC would necessitate the assessment of tumor development in the VillinCreER/0/BrafV600E-LSL/+ or other models of BRAF-driven colorectal carcinogenesis." (PMID 37735514, 2023). "Unfortunately, the number of inclusions in this study did not enable us to stratify MSI tumours according to BRAF-mutation." (PMID 37344790, 2023). "Among them, only one patient underwent genetic testing and showed no BRAF V600E mutation in the tumor." (PMID 37454137, 2023).
tumor (continued). "New therapeutic pathways for the treatment of this tumor type are still being identified with new emerging potential targets such as isocitrate dehydrogenase (IDH), fibroblast growth factor receptor 2 (FGFR2), or BRAF mutation." (PMID 37374378, 2023). "In five cases of adult MST, genetic testing was performed in only one case, and no BRAF V600E mutation was detected in the tumor." (PMID 37454137, 2023). "This was also consistent with previous studies that showed no survival difference between BRAF mutation-positive or -negative tumours." (PMID 38201554, 2023). "In vivo and in vitro studies, applying a BRAF-targeted inhibitor (one of MAPK/ERK signaling inhibitors) could increase the expression of tumor antigens and the abundance of tumor-infiltrating immune cells." (PMID 37345194, 2023). "STRA6 may contribute to the progression of BRAF-mutant PTC via regulation of immunosuppressive tumor microenvironment and activation of oncogenic pathway." (PMID 36843593, 2023). "We first used this workflow on tumor cell lines, including H1650, PANC-1, and HT-29, to assess whether the most common genetic mutations in EGFR (19del), KRAS (G12D), and BRAF (V600E)." (PMID 37849806, 2023). "Moreover, studies have shown that the degree of tumor dedifferentiation correlates with the magnitude of activation of the MAPK pathway, and that BRAF V600E mutations lead to greater MAPK activation than RAS or RTK alterations." (PMID 37435488, 2023). "As the majority of patients present with IVC disease or develop distant metastasis during the course of disease progression, our data suggest that neoadjuvant BRAF-directed therapy results in a systemic reduction in tumor burden to allow for surgical resection of primary disease." (PMID 36762947, 2023). "The mutational status of these tumours was also accessible for TERTp, NRAS, and BRAF genes." (PMID 37568724, 2023). "The effect of coincident tumor suppressor inactivation could generally be reduced due to diminishing-returns epistasis in fast-growing BRAF V600E-driven tumors." (PMID 37828026, 2023). "A better understanding of tumor-specific differences in a molecular mechanism might help advance the strategy to combine immune checkpoint inhibitors with BRAF/MEK inhibitors." (PMID 37834284, 2023). "Two patients showed NRAS mutations in the plasma, but not in their tumor biopsy sample, while only one patient showed such a discrepancy for BRAF gene mutations." (PMID 37176143, 2023). "Furthermore, the BRAF mutation is associated with the production of CXCL8, a proinflammatory chemokine that can promote tumor proliferation, angiogenesis, and metastasis." (PMID 37014331, 2023). "Interestingly, the distribution of BRAF-driven tumor sizes was strikingly different from that of other oncogenic contexts." (PMID 37828026, 2023). "We next checked whether genes of the tumor progression-related NF-κB signature evidenced in BRAF-PTCs were actually regulated by RelA or RelB in BRAFV600E cell line models." (PMID 37973791, 2023). "Furthermore, we provide an overview of the main mechanisms of resistance to BRAF inhibitors and circulating tumour biomarkers." (PMID 37627054, 2023). "However, despite sharing the same—and most frequent—BRAF mutation (i.e., BRAFV600E), different tumour types display a heterogeneous responsiveness to BRAFi-based therapies." (PMID 37198319, 2023). "In multivariable Cox proportional hazards analyses, COMP expression in the cancer cells (p=0.029) and in the stroma (p=0.021) was associated with reduced patient OS with a hazard ratio of 1.2, after adjustment for BRAF and KRAS mutations, tumor differentiation, TNM-stage, and vascular invasion." (PMID 37207219, 2023).
tumor (continued). "However, the patients’ BRAF status in the research investigations is usually based on the primary tumour tissue samples." (PMID 38201554, 2023). "Inhibiting BRAF signaling has been demonstrated to reduce myeloid-derived suppressor cells, increase the recruitment of tumor-infiltrating lymphocytes, enhance neoantigen presentation on antigen-presenting cells, and collectively enhance anti-tumor immune responses." (PMID 37920463, 2023). "The authors showed that in the population of Korean patients, BRAF V600 mutation does not correlate with prognostic factors such as extrathyroidal extensions, multifocality, tumor size, gender, age and lymph node metastases." (PMID 37547301, 2023). "It has been hypothesized that KRAS, NRAS, or BRAF mutations and deficient mismatch repair status (MMR) might be partially responsible for the prognostic effect of primary tumor location." (PMID 37071802, 2023). "Furthermore, RAS and BRAF mutations were associated with worse DFS compared with MSI status, independently of clinical factors, stage, and tumor burden." (PMID 37667167, 2023). "In addition, those with metastatic colon cancer should have tumor somatic genotyping for KRAS, NRAS, and BRAF mutations." (PMID 35837788, 2023). "Therefore, TERT mRNA expression should be higher in tumor tissues when the TERT promoter and BRAF mutations coexist." (PMID 37296851, 2023). "Interestingly, the combination of BRAF V600E and CDKN2A loss likely leads to tumor transformation and higher tumor grade." (PMID 38318325, 2023). "From a biological standpoint, it is worth noting that both BRAF and NRAS mutations are present in nevi, suggesting that such mutations might represent early events that could already be present in all tumor cells." (PMID 38003476, 2023). "KRAS is the most common driver oncogene in CRC and many other tumors, based in large part on its ability to simultaneously activate BRAF, PI3K, and other signaling effectors, which collaborate to induce tumor proliferation, survival, and other processes associated with progression." (PMID 38001126, 2023). "Regorafenib is an oral inhibitor of several kinases involved in tumor angiogenesis (VEGFR1-3 and TIE2), oncogenesis (KIT, RET, RAF1, and BRAF), and in the interaction between tumor and microenvironment (PDGFR, FGFR), and tumor immunity (colony-stimulating factor 1 receptor [CSF1R])." (PMID 37071295, 2023). "The signaling plasticity offered by these SRC-dependent mechanisms may usurp and/or reinforce cell-autonomous pathways that drive tumor survival while bypassing other dependencies, including under the influence of BRAF/MEK or EGFR targeted therapies." (PMID 36759733, 2023). "In the BRAF V600− subset, Tumor Mutational Burden (TMB) was twice that in responders vs. non-responders." (PMID 36901733, 2023). "Therefore, it is recommended only to use anti-EGFR drugs in patients whose tumours display BRAF/KRAS/NRAS WT sequences." (PMID 36758042, 2023). "Thus, the compound was active in the low nanomolar range in both wild-type, and BRAF- and KRAS-mutated tumor models in vitro and in vivo." (PMID 37830744, 2023). "After progression to first-line immunotherapy in MSI-H, we prefer to offer a second-line doublet (fluoropyrimidine with irinotecan or oxaliplatin) with bevacizumab if raf murine sarcoma viral oncogene homolog B1 (BRAF) wild-type, especially if rat sarcoma (RAS) mutated or right-sided tumours." (PMID 37377686, 2023). "Interestingly, in five cases with BRAF V600E variants, the model concordantly predicted a Group 1 classification where consensus clustering had failed to, suggesting the model may be able to segregate cases with low‐tumour content that typically cluster alongside control brain." (PMID 36843390, 2023).
tumor (continued). "At tolerable doses, an anti-tumor response of 12.1% was observed, irrespective of BRAF mutation status." (PMID 37370834, 2023). "There are several established prognostic factors in thyroid cancer, such as age, sex, tumor histopathology, tumor size, lymphovascular invasion, extrathyroidal extension (ETE), lymph node metastasis (LNM), distant metastasis, BRAF mutation, and TERT promoter mutation." (PMID 37383396, 2023). "Patients with BRAF-wild type tumor and without underlying HT had similar incidences of recurrence and non-recurrence (p = 0.84)." (PMID 37190300, 2023). "Furthermore, rare preclinical studies proposed a higher sensitivity of those tumor cells to radiation and an increased radiosensitization in the case of concomitant BRAF inhibition." (PMID 36831610, 2023). "Mutations in the RAS-RAF-MEK-cascade, among which BRAF-mutations, induce EMT by allowing downstream effectors to promote the expression of transcription factor regulating EMT, leading to a mesenchymal phenotype of the tumour." (PMID 37344790, 2023). "Older adults also have tumor characteristics with inferior outcome, such as more right-sided primaries, non-favorable metastatic sites, BRAF mutations, deficient mismatch repair, etc.." (PMID 37240646, 2023). "Indeed, the first report of MEK/BRAF inhibitors for treatment of refractory PCP described a tumor reduction of 85% and 81% of the solid and cystic parts of the tumor, respectively." (PMID 36748936, 2023). "The obtained data were highly concordant with the results of the visual inspection of the slides, thus suggesting that KRAS/BRAF mutations are not mosaic but present in all tumor cells." (PMID 37686416, 2023). "In-frame BRAF exon 12 deletions are increasingly identified in various tumor types." (PMID 37656784, 2023). "The three MLH1 methylated EOCRCs each showed loss of MLH1/PMS2 protein expression by IHC, showed high levels of MLH1 methylation in their tumours (β = 0.34, 0.42, 0.67) and did not have the BRAF p.V600E mutation or CIMP-high." (PMID 37270516, 2023). "Three patients had KRAS mutations (type not specified) and two presented tumours harbouring BRAF mutations (type not specified)." (PMID 36879000, 2023). "Interestingly, the overall tumor suppressive landscapes of BRAF- and EGFR-driven lung tumors were dramatically different from each other as well as from oncogenic KRAS-driven tumors." (PMID 37828026, 2023). "BRAF inhibitors (BRAFi) appear to be able to modulate the tumor microenvironment (TME)." (PMID 37569757, 2023). "FURIN knockdown in the BRAF mutant cell line led to reduced tumor growth and increased apoptosis." (PMID 36799665, 2023). "MLH1 promoter methylation testing (or BRAF mutation testing for CRC;) and NGS analysis of the tumor may be useful in clarifying the MMR gene mutation status." (PMID 37874379, 2023). "Furthermore, targeted therapy (e.g. BRAF inhibition in BRAFV600E mutant tumours) has been shown to enhance this phenomenon." (PMID 37608347, 2023). "Additionally, we discuss the possible role of the BRAF gene in the pathophysiology of PTC-associated MCD in this case and highlight the importance of tumor screening." (PMID 37234240, 2023). "This may indicate that control of tumor growth is dominated by targeted therapies and that a constant influence of the BRAF/VEGFA targeting on TME should be required to exploit the best efficacy of anti‐PD‐1 treatment." (PMID 37183363, 2023). "We also observed tumor samples with co-occurring driver variants in EGFR, KRAS, and BRAF genes (seven patients with KRAS/EGFR variants; four patients with BRAF/KRAS; one patient with BRAF/EGFR/KRAS)." (PMID 37483495, 2023). "Indeed, the anti-tumor effects and immune modulatory effects of a BRAF inhibitor were observed in the model." (PMID 37545523, 2023). "The different benefit from anti-EGFR according to primary tumor site in RAS/BRAF wt mCRC patients may be also explained by a heterogeneity of primary resistance profile." (PMID 36895480, 2023).
tumor (continued). "Interestingly, while BRAF/MEKi or anti-PD-1 antibody alone had minimal effect on tumor volume compared with vehicle, combined BRAF/MEK/PD-1 inhibition produced a more substantial and sustained reduction in tumor growth." (PMID 36702949, 2023). "Furthermore, the correlation between BRAF, KRAS, NRAS mutations, and FAP and CXCR4 in both the primary tumor and the first metastasis were examined." (PMID 37892020, 2023). "Nowadays, testing for somatic tumor mutations in RAS and BRAF is mandatory to select the most appropriate treatment for CRC patients, and characterization of microsatellite instability (MSI) status of CRC tumor is assessed to evaluate the use of immune checkpoint inhibitors." (PMID 36900260, 2023). "The hazard ratio for developing PM and having a BRAF-mutated tumor was statistically not significant." (PMID 36672497, 2023). "The RASSF1 gene showed hypermethylation in tumor tissue in both BRAF mutant and wild-type cases." (PMID 36975440, 2023). "Inhibition of the BRAF-MEK pathway, and decreased tumor cell survival in BRAF-mutants." (PMID 36675114, 2023). "If a more infiltrative tumor pattern is found, the recent molecular knowledge about genetic mutations such as KIAA1549-BRAF fusion and BRAF-V600E mutation could offer additional targets for therapies." (PMID 37685588, 2023). "Several previous studies suggest a better prognosis for MSI tumours, even independent of presence of a BRAF-mutation." (PMID 37344790, 2023). "BRAF mutation is a common event in PTC, and its presence indicates tumor progression." (PMID 37361050, 2023). "It has been hypothesized that RAS, BRAF mutations, or deficient mismatch repair status (MMR) might be responsible for the prognostic effect of primary tumor location (PTL)." (PMID 37071802, 2023). "Investigations have examined GAPDH’s interaction with mutated KRAS and BRAF, suggesting that GAPDH suppression via vitamin C may disrupt tumor growth." (PMID 38134011, 2023). "Still our data suggests that in combination with a targeted immunotherapy, especially in BRAF-positive tumour, visceral resection could provide a promising additional therapeutic option for patients." (PMID 36680624, 2023). "In another recent study, cells developing resistance to the drug triplet maintained both the BRAF V600E mutation and KRAS mutation (G12D or G13D), demonstrating that the coexistence of both mutations confers greater treatment resistance to the tumor." (PMID 37958416, 2023). "This study reveals that SMAD4 is a critical tumor suppressor for BRAF-driven serrated tumors." (PMID 38136364, 2023). "Previous studies of biomarkers in tumor tissues have shown that the mutation status of genes known to be associated with CRC carcinogenesis (NRAS, KRAS, and BRAF) and defects in the DNA mismatch repair system, exert substantial effects on the treatment decision." (PMID 36394150, 2023). "Regarding patients with BRAF-mutant tumours, the CheckMate 069 trial showed that nivolumab plus ipilimumab is an effective first-line treatment option regardless of BRAF mutational status." (PMID 37404764, 2023). "When BRAF p.V600E is present in tumor cells it usually promotes a modest proliferative cell capacity, probably explaining the better prognosis of patients, who experience an improved survival outcome with an indolent tumor course." (PMID 36831610, 2023).